FAM91A1 (family with sequence similarity 91 member A1)
Description:
As component of the WDR11 complex acts together with TBC1D23 to facilitate the golgin-mediated capture of vesicles generated using AP-1.
Synonyms: FLJ23790
Tractability: PROTAC: ubiquitination databases record sites on it; its protein half-life has been measured.
Gene: Protein-coding gene on chromosome 8 (123,768,439 to 123,815,452, forward strand). Ensembl gene ENSG00000176853.
Subcellular location: Golgi apparatus, trans-Golgi network; Cytoplasmic vesicle
Subcellular location (Human Protein Atlas): Microtubules; Nucleoplasm
Pathways (Reactome):
Signal Transduction: RHOH GTPase cycle
Gene Ontology:
Molecular function: protein binding
Biological process: intracellular protein transport
Cellular component: cytoplasmic vesicle; trans-Golgi network; Golgi apparatus
Genetic constraint (gnomAD): Loss-of-function variants: 25 observed, 75.6 expected, observed/expected ratio (o/e) 0.33, 90% interval 0.24 to 0.46. The upper end of that interval is the gene's LOEUF score, 0.46, which puts it in group 2 of 6, group 1 being the genes least tolerant of losing a copy. Missense variants: 598 observed, 860.16 expected, observed/expected ratio (o/e) 0.7, 90% interval 0.65 to 0.74. Synonymous variants: 258 observed, 301.11 expected, observed/expected ratio (o/e) 0.86, 90% interval 0.77 to 0.95.
Homologues: Orthologues: chimpanzee FAM91A1 (99% identical), macaque FAM91A1 (98% identical), dog FAM91A1 (97% identical), rabbit FAM91A1 (96% identical), mouse Fam91a1 (95% identical), guinea pig FAM91A1 (95% identical), rat Fam91a1 (95% identical), pig FAM91A1 (94% identical), tropical clawed frog fam91a1 (85% identical), zebrafish fam91a1 (79% identical), Caenorhabditis elegans F33H2.2 (42% identical), Drosophila melanogaster CG7600 (42% identical).
Diseases named in the same sentence as FAM91A1 in open-access papers:
FAM91A1 is named in the same sentence as 6 diseases in open-access papers, as found by Europe PMC text mining. Sharing a sentence is not in itself a finding about the gene and the disease. The quoted sentences say what the papers report.
breast carcinoma (1 paper, 2024). "FAM91A1 was recently identified as a candidate target gene for breast cancer risk signal." (PMID 38371918, 2024).
congenital heart disease (1 paper, 2025). A heart disease that is present at birth. "Furthermore, the LOF variants identified in the low-LOUEF score genes FAM91A1, INTS8, and PDE2A have not been previously linked to congenital heart disease and are newly reported in this study." (PMID 40406060, 2025).
gastric cancer (1 paper, 2019). A primary or metastatic malignant neoplasm involving the stomach. "Significant gains of genes ATAD2, DSCC1, FAM91A1, and MYC brought to the enrichment of the Gastric Cancer Network 2 pathway, and ATAD2 is a cancer-associated protein which can also induce the expression of Cyclin D1 and MYC." (PMID 31921654, 2019).
osteosarcoma (1 paper, 2022). A usually aggressive malignant bone-forming mesenchymal neoplasm, predominantly affecting adolescents and young adults. "However, we found that FAM91A1 is a risk factor for osteosarcoma; thus, its functions need to be further studied." (PMID 35610231, 2022).
cancer (3 papers, 2019 to 2024). A tumor composed of atypical neoplastic, often pleomorphic cells that invade other tissues. "DCAF13 was strongly correlated with SLC25A32 in most cancers (R = 0.75), followed by FAM91A1 (R = 0.69) and TAF2 (R = 0.68)." (PMID 39624160, 2024).
tumor (2 papers, 2022 to 2023). "The top 100 genes that correlated with NUDCD1 expression indicated 4 common members: FAM91A1, DCAF13, MED30 and DDX21, and their corresponding expression in different tumor types could be established." (PMID 37338527, 2023). "Whether FAM91A1 is related to tumours has not yet been reported." (PMID 35610231, 2022).